TNF (tumor necrosis factor)
Diseases named in the same sentence as TNF in open-access papers (continued):
Sharing a sentence is not in itself a finding about the gene and the disease.
tumor (continued). "TAMs secrete cytokines, including interleukin-6 (IL-6), interleukin-10 (IL-10), tumor necrosis factor-α (TNF-α), and interferon-γ, which have been shown to promote tumor cell growth." (PMID 30034397, 2018). "Tumors after TNFα GET were smaller and necrosis was more evenly distributed throughout the tumor compared to in the control tumors, where the necrosis was mainly centrally located." (PMID 29468364, 2018). "This prediction is in line with higher cytokine (IFN-γ, TNF-α and MCP-1) levels found in the serum of tumour bearing VSV∆51-B2 treated immune-competent mice." (PMID 29921327, 2018). "After 24 h of in vitro restimulation, we predominantly detected CD4+ T cells with a Th1 profile, in both hCT26 tumor-bearing (TB) and tumor-free (TF) vaccinated groups, secreting IFN-γ, IL-2, TNF-α, and GM-CSF." (PMID 30483475, 2018). "Attention is particularly focused on finding new ways to induce the production of proinflammatory cytokines, including TNF or interferon (IFN), which have the capacity to destroy tumor cells." (PMID 29682586, 2018). "Consistent with our microarray analysis, the IFN-γ, TNF-α and MCP-1 concentrations from the serum of the RENCA tumour-bearing Balb/c mice were significantly increased for the VSV∆51-B2 treated mice compared to VSV∆51-GFP treated mice." (PMID 29921327, 2018). "Tumor necrosis factor-α (TNF-α) is an important cytokine that participates in inflammation, and the dynamic balance of immune cells and tumor progression." (PMID 29531823, 2018). "Conversely, sunitinib treatment activated CD8+ T cells from immunized tumor-bearing mice, allowing epitope-I and -IV to effectively stimulate CD8+ T cells producing IFN-γ and TNF-α." (PMID 30123861, 2018). "The expression of this molecule on the tumor cell surface triggers NKp30-mediated killing and the production of IFN-γ and TNF-α." (PMID 29740448, 2018). "In a subcutaneous tumor model of CT26, tumor necrosis factor-alpha enhanced the tumorigenic ability of the cells, and again this was inhibited by Kanglaite." (PMID 29467927, 2018). "We have shown that the pro-inflammatory cytokines IFN-γ, TNF-α, and IL-2 enhance the capacity of TCR-transfected T cells to lyse tumor target cells;28 by contrast, the addition of autologous monocytes mimics the PD-L1hi environment of the liver." (PMID 30217730, 2018). "In overnight cytokine release assays in which CAR T cells were challenged with the CD33+ tumor cells HL-60, MOLM-14 and KG-1a, CAR33VH elicited IFN-gamma, TNF-alpha and IL-2." (PMID 30524966, 2018). "Tumor samples obtained from ST2KO mice presented lower levels of IFN-γ, TNF-α, IL-10, and IL-17, while the production of IL-12, IL-4, IL-13 and TGF-β was similar between tumor skin samples obtained from wild type and ST2KO mice." (PMID 30112116, 2018). "Moreover, APG-1387 might also enhance the tumor inhibitory effect of TNF-α and TRAIL in HCC CSCs." (PMID 30459627, 2018). "This treatment not only enhance the tumor cell killing, but also the activation of γδ T cells as seen by augmented CD69, CD25, IFNγ, and TNFα expression." (PMID 30038626, 2018). "Many potential cytotoxic mediators produced by neutrophils, including TNF-α, NO, and H2O2, can contribute directly to their tumor-suppressive activity." (PMID 30473691, 2018). "Because it has been reported that the tumour‐derived factors such as CCL2, SDF1, IL6, TNFα, VEGF, G‐CSF, TGFβ, and CXCL1 function in the pre‐metastatic phase, we applied those factors to HepELs in the tumour‐bearing mouse liver in vitro." (PMID 29930175, 2018). "Most interestingly, in murine cancer models, high-IDO activity, resulting in accelerated tumor progression, is associated to immune responses and to high expression in the tumor microenvironment of pro-inflammatory cytokines, including IFN-γ and TNF-α." (PMID 29896191, 2018). "TNF-α in the tumor microenvironment acts as an inflammatory mediator that triggers the EMT of tumor cells and promotes tumor metastasis." (PMID 30060453, 2018).
tumor (continued). "Previous studies showed that IFN-γ, TNF-α, and IL-2-expressing CD8+ T cells are instrumental in anti-tumor immune response." (PMID 30619765, 2018). "This phenomenon was related to a lower capacity of T cell secretion of TNF-α and Interferon-Υ (IFN-γ), which are important cytokines mediating T cell antitumor immunity and lower T cell-mediated tumor cytotoxicity." (PMID 29315242, 2018). "Adipocyte-derived factors, such as leptin, interleukin-6 (IL-6), adiponectin, tumor necrosis factor (TNF-α), monocyte chemotactic protein-1 (MCP-1) and endotrophin (ETP), function within the tumor microenvironment to promote tumor progression." (PMID 30563531, 2018). "In the combinational therapy, the Treg cells in the tumor were decreased from 13.2% to 6.8%, the CD8+ T effector cells significantly elevated, and the secretion of proinflammatory cytokines IFN-γ and TNF-α was significantly increased." (PMID 30406152, 2018). "We evaluated TLR2, TLR4 and TNF-α mRNA expression in peritoneal macrophages and serum TNF-α protein levels at a single time-point after tumor induction and after therapeutic intervention with zymosan." (PMID 29588627, 2018). "Human interdigitating DCs (iDCs), incubated with H-1PV-induced tumor cell lysates, exhibited increased expression of TLR3, TLR9, and NF-κB and produced higher amounts of TNF-α compared to uninfected human melanoma (SK29Mel) cells in ex vivo model." (PMID 30413032, 2018). "A set of tumor cytotoxic genes were up-regulated in CIK cells, including GZMB, FASL, PRF1, TNFα, CD40L, and IFN-γ." (PMID 30333226, 2018). "Cytokines, chemokines, and growth factors such as IL-6, IL-8, IL-1β, TNF-α, TGF-β, GM-CSF, VEGF, and angiopoietins have been shown to promote angiogenesis and tumor metastasis." (PMID 29541344, 2018). "While cell death due to ROS in combination with endoplasmic reticulum (ER) stress leads to ICD in tumor cells, apoptosis induced by exposure of tumor cells to IFN-γ and TNF-α is less immunogenic." (PMID 30233579, 2018). "On the other hand, MSCs promoted cancer in progressive stages due to the elevation of proinflammatory cytokines (IFNγ, TNFα, IL6 and IL1β) expression in the tumor microenvironment." (PMID 30346985, 2018). "On the other hand, tumor growth was slightly reduced in the KLT injected mice, but KLT had only a mild inhibitory effect on TNF-α-induced EMT." (PMID 29467927, 2018). "The serum levels of TNF and IFN-γ significantly increased in HT29 tumor-bearing mice at 1 h and at 3–6 h, respectively." (PMID 29690614, 2018). "The combined immunotherapy potently induced M1 markers (CD40, CD80, CD86, MHC II, TNFα and IL12) in vivo and synergised with chemotherapeutic regimens potently inhibiting tumour growth in melanoma and neuroblastoma mouse models." (PMID 30577495, 2018). "The addition of TNF-α induced the overexpression of cell adhesion molecules in HUVEC monolayer, which can better mimic the endothelial barrier under tumor environment." (PMID 30465444, 2018). "Mice were CO2-euthanized and serum TNF-α level, TLR-2 and TLR-4 expression in peritoneal macrophages and tumor growth measured." (PMID 29588627, 2018). "Oncolytic adenoviruses modified to express IL-15 and RANTES or IL-2 and TNF-α have been shown to increase the accumulation and survival of CAR-T cells in the tumor microenvironment." (PMID 30405639, 2018). "TNF-α, generally released by activated macrophages, is a key player modulating inflammatory responses in the HCC tumor microenvironment." (PMID 29464083, 2018). "On the other hand, tumor-bearing TLR4−/− TB mice presented less adipocyte atrophy and a reduction in the number of TNF-α and CD-68 positive cells in scAT when compared to WT TB group." (PMID 30575787, 2018). "Pro-angiogenic macrophages promote tumor growth and invasion by secreting factors (for example, VEGFA, tumor necrosis factor alpha [TNFα], and interleukin-2 [IL-2]), eventually resulting in resistance to bevacizumab." (PMID 29560266, 2018).
tumor (continued). "CTLs activated by derived from tumor-associated antigen HLA-restricted epitopes play a key role in specifically killing cancer cells through directly lysing tumor cells and secrete cytokines such as IFN-γ, TNF-α, and IL-2." (PMID 30596107, 2018). "Proliferating tumor cells can secrete prostaglandins, PTH, activated vitamin D, IL-6 and tumor necrosis factor (TNF), leading to an increase in RANKL expression on OBs and BM stromal cells, which stimulates OC numbers, survival and activity." (PMID 29461491, 2018). "Here, we used TGFβ1 and TNFα to experimentally induce EMT, increase motility, migration, and invasion of tumor cells." (PMID 30356176, 2018). "Because a TNF-α-neutralizing agent was shown to be able to inhibit the suppression of tumor immunity by type II NKT cells, TNF-α is also involved in this signaling pathway." (PMID 29520281, 2018). "Cytokines like, TGF-β and TNF-α are secreted in the HCC tumor milieu, which alongside other cytokines, growth factors and tumor infiltrating leukocytes invariably create a chronic inflamed state contributing significantly to the progression of the disease." (PMID 29464083, 2018). "In a small subset of tumor cell lines, TWEAK induces apoptosis by triggering TNF production and subsequent stimulation of TNFR17,8." (PMID 30349023, 2018). "Since IL-6 acts differently from TNF-α, and can be replaced by other cytokines, we think that TNF-α is the first endogenous instigator for the sequence of cytokine cascade from IL-1 to IL-6 and subsequently returns to TNF-α in tumor promotion." (PMID 30341686, 2018). "Tumour Necrosis Factor alpha (TNF-α) is a major proinflammatory cytokine produced within the TME, which was originally characterised for its ability to induce tumour death." (PMID 29725601, 2018). "Th1 cytokines TNF-α and IFN-γ are increasingly recognized as critical mediators of CD4+ T-cell-driven anti-tumor activity." (PMID 29796172, 2018). "Comparison between the primary tumor myeloid lineage cells and the metastatic myeloid lineage cells showed elevated levels of CC2, CC3, CC4, CXCL8 and TNF in the primary tumor." (PMID 30383866, 2018). "Tumor volume in the TNF-α + KLT group was reduced, suggesting that KLT offsets part of TNF-α effect." (PMID 29467927, 2018). "Tumor progression and circulating levels of VEGF and TNF-α were greater in the presence of chronic inflammation than acute inflammation." (PMID 30034291, 2018). "Anti-tumor N1-like TANs produce elevated amounts of tumor necrosis factor alpha (TNF-α), macrophage inflammatory proteins-1 alpha (MIP-1α), hydrogen peroxide and NO that are cytotoxic to tumor cells." (PMID 30619850, 2018). "NF-κB signaling in cancer cells can be activated by factors such as IL-1β, TNFα and IL-8, IL-6 and MCP-1 secreted by cells in the microenvironment of the tumor, e.g. macrophages or adipocytes." (PMID 29930291, 2018). "TNFα GET was less effective, having only a moderate effect on tumor growth (tumor growth delay of 6 days) and a low cure rate." (PMID 29468364, 2018). "Our results revealed that cytokines in ATC cell lines and tumor tissues, including IL-8, TGF-α and TNF-α, were down-regulated by suppression of UHRF1." (PMID 30174788, 2018). "Upregulation of MHC class II on autologous tumor cells stimulated CD4+ TIL to produce both IFN-gamma (4.0%) and TNF-alpha (5.9%)." (PMID 30400835, 2018). "Interleukin-2 (IL-2), interferon-γ (IFN-γ), and tumor necrosis factor-α (TNF-α) levels dose-dependently increased in both serum and ascites from PRP-treated, H22 tumor-bearing mice compared to control mice." (PMID 29735884, 2018). "We used multiplex ELISA to demonstrate the presence of IL1B, IL6, IL8, IL10, IL18, TNF and IFNG in the cystic fluid and whole ACP tumour protein lysates." (PMID 29541918, 2018). "Inflammatory cytokine generation is a critical process in the regulation of inflammation and the advancement of tumours, and this study's findings corroborate CIE's capacity to inhibit TNF-α and IL-1β." (PMID 28491105, 2017).
tumor (continued). "Classically, Th1 cytokines, such as interleukin-6 (IL-6), IL-12, tumor necrosis factor-α (TNF-α), and interferon-γ (IFN-γ), promote immune responses to intracellular pathogens and tumor cells." (PMID 28858203, 2017). "Intratumoral expression of IFN-γ or TNF-α induces monocyte chemoattractant protein-1 (MCP-1) production, which enhances T cell infiltration into tumor tissues." (PMID 28002796, 2017). "The danger signals thereby induce the production of inflammatory cytokines such as PDGF, TNFα, CCR8, and CCR2 within the tumor microenvironment, and consequently enhance MSCs swarming into the tumor location(s)." (PMID 29326689, 2017). "In this study, the authors show that Smac mimetics can synergize with immune checkpoint inhibitors to control tumour growth in mouse cancer models, including aggressive CNS tumours, in a cytotoxic CD8+ T-cell- and TNFα-dependent manner." (PMID 28198370, 2017). "We found that both tumor-derived Lin-EpCAM-CD73+CD90+ cells and their matched normal counterparts upregulate PD-L1 following exposure to TNFα and IFNγ, as shown in histograms overlays." (PMID 28878242, 2017). "In mouse models of carcinogenesis, neutralization of TNF resulted in reduced MDSC accumulation and delayed the tumor growth." (PMID 28890718, 2017). "And GE11-Ori-Se NPs was found to significantly inhibit the tumor growth via inhibition of tumor angiogenesis by reducing the angiogenesis-marker CD31 and activation of the immune system by enhancing IL-2 and TNF-α production." (PMID 29019267, 2017). "In this context, we observed a significant increase of TNF-α expressing CD4+ and CD8+ T-cells, indicating that these T-cells can directly induce SMC-mediated tumour cell death." (PMID 28198370, 2017). "On the opposite, soluble factors present in the tumor microenvironment such as TGF-β, TNF-α, IL1β and FGF promote the expression of MMPs by fibroblasts." (PMID 28423623, 2017). "The TNF-α autocrine-paracrine loop can induce constitutive activation of NF-κB and YY1 in tumor cells." (PMID 28476134, 2017). "The TNF autocrine-paracrine loop induces constitutive activation of transcription factors NF-κB and the transcription repressor YY1 in tumor cells, which both downregulate Fas and induce resistance to FasL-induced apoptosis." (PMID 28476134, 2017). "T cells were deemed tumour reactive when positive for either CD107a, IFN-γ or TNF-α or a combination of these (see methods section)." (PMID 28423678, 2017). "We further measured the level of cytokines TNFα, IL-1β, IL-6, IL-17, IL23 and Cox-2 in tumor and normal tissues collected from the mouse colon using RT-qPCR." (PMID 28704539, 2017). "Immunohistochemistry (IHC) study was performed on type I EC tumor samples using five adipokines (SPARC, RBP4 (Retinol Binding Protein 4), adiponectin, TNF α, IL-6) and hormonal receptors (estrogen receptor and progesterone receptor)." (PMID 28505082, 2017). "The combination of COX‐2 inhibitors, TNF‐α inducer, or anti‐angiogensis agents can potentiate the PDT response and lead to more efficient tumor inhibition." (PMID 28105389, 2017). "Some CD4+NKG2D+ T cells secrete IFN‐γ and TNF‐α to promote inflammation, but others produce TGF‐β and FasL to facilitate tumour evasion." (PMID 28224733, 2017). "Therefore, on the whole, the presence of both TNFα and TGFβ1 at tumor sites, combined with the factors they induce in MSCs (as we have demonstrated), may have pro-malignancy effects that act on the TME as well as directly on the cancer cells, to promote their pro-invasive potential." (PMID 28553282, 2017). "Tumour cell apoptosis is controlled by HSP90, principally through its action on TNF-mediated signalling pathways and on nuclear factor-κB." (PMID 29089667, 2017). "On the other hand, we found the expression of TNF-α, TRAF2 and TRAF4 was enhanced in the primary tumor as time goes on." (PMID 28774312, 2017).
tumor (continued). "Relevantly, it was reported that interaction of TNF-α and TNF receptor 1 promotes gastric tumorigenesis via the induction of NAD(P)H oxidase (Nox) in tumor cells." (PMID 28825631, 2017). "The expression patterns of TNF-α, IFN-γ and IL-17 were consistent with the results of the cytokine array assay used to evaluate the tumor microenvironment." (PMID 28399860, 2017). "The responsiveness of these lymph node cells to the premalignant lesion or tumor lysates was then measured by their production of IFN-γ, IL-17 and TNF-α." (PMID 28574425, 2017). "Our study showed that both P.y-WT and P.y-GPC3 infection increased high levels of proinflammatory cytokines, such as IL-2, TNF-α and IFN-γ, which leads to activation of defense response effectors against tumor cells." (PMID 28445973, 2017). "Our data reveal that the truncated BAFF–E7 vaccine with defect of the furin cleavage site located between the transmembrane domain and TNF homology domain lost the ability of CTL activation and tumor growth inhibition." (PMID 28423693, 2017). "In the last decade, it was well described that macrophages secrete matrix-remodeling proteins, cytokines and chemokines (e.g. MMP, TNF-α, EGF, TGFβ) that can induce the migration and proliferation of tumor cells, 37–39." (PMID 28790339, 2017). "This study aimed to determine if tumor-therapeutic effects against CT26 and RenCa described for SL7207 can be equally induced via avitalized bacteria, LPS or recombinant TNF-α, likely accounting for the dominant adjuvant pathway of gram-negative bacteria." (PMID 28445131, 2017). "Autologous tumor-specific immune response was seen in two of the three, manifested by IL-5 (1 patient after 3 doses), and IFN-γ, TNF-α, IL-5, IL-10 (after 4 doses in one patient)." (PMID 29258618, 2017). "BAX69 abrogates MIF signaling and MIF-mediated secretion of cytokines (IL-1β, TNF-α, etc.)and inhibits proliferation of MIF overexpressing tumor cells, together with the antiproliferative effects of panitumumab (anti-EGFR mAb)." (PMID 29312320, 2017). "Together these results revealed that TGF-β-type cytokines cooperate with TNF and IL-1β cytokines in the stimulation of MMP9 expression in tumor cells." (PMID 28423685, 2017). "A human mAB is used to target L19-TNF, an armed antibody that selectively targets human TNF to EDB of fibronectin on tumor blood vessels." (PMID 28574434, 2017). "In a healthy brain, TNF-α is responsible for dendritic cell (DC) maturation whereas, in tumorigenic conditions its expression correlates with GBM tumor grade." (PMID 28346397, 2017). "And in nude mice xenograft model, GE11-Ori-Se NPs significantly inhibited the tumor growth via inhibition of tumor angiogenesis by reducing the angiogenesis-marker CD31 and activation of the immune system by enhancing IL-2 and TNF-α production." (PMID 29019267, 2017). "The results of this study suggested that TNF-α content in the serum was at a low level, while the protein expression of TGF-β1 in tumor tissue was at a high level in our tumor model group." (PMID 28388901, 2017). "When tumour supernatants were substituted by a combination of purified TGF-β and TNF-α, similar results were obtained with CpG-activated CAL-1 cells." (PMID 29030552, 2017). "Inducers of the EMT such as TGF-β, tumor necrosis factor alpha (TNF-α), interleukin 6, Akt, and β-catenin are also known cargo of tumor-derived EVs." (PMID 28848498, 2017). "Intravenous injection of MSCs reduced the presence of CD3+ T lymphocytes, CD4+ T helper cells, CD68+ macrophages, TNF-α-producing, and IL-17-producing cells in the lungs of LLC1-treated mice 28 days after tumor induction." (PMID 28798777, 2017). "This study provides for the first time the evidence that demonstrates the importance of the TNF-α-VEGFR-2 axis in endothelial morphogenesis and tumor growth." (PMID 29232409, 2017).